DOCK8 (dedicator of cytokinesis 8)
Diseases named in the same sentence as DOCK8 in open-access papers (continued):
Sharing a sentence is not in itself a finding about the gene and the disease.
infection (12 papers, 2012 to 2025). The state of being infected such as from the introduction of a foreign agent such as serum, vaccine, antigenic substance or organism. "Here, we describe a patient with DOCK8 deficiency and severe, progressive herpetic infections refractory to therapy with valacyclovir." (PMID 39044832, 2024). "Our case describes a 6-year-old patient with DOCK8 deficiency and severe, progressive herpetic infection." (PMID 39044832, 2024). "The EBV-driven lymphoproliferative disease along with the infection history in the brother led to the diagnosis of DOCK8 deficiency and curative hematopoietic stem cell transplants." (PMID 28293550, 2017). "Thus, DOCK8+Tfh cells newly generated after repeated infection fulfill the criteria (i), (ii) and (iii) as the cause of SLE." (PMID 40710333, 2025). "The clinical phenotype of both DOCK8 and IFNAR1 deficiencies includes susceptibility to infection with various viruses." (PMID 39098944, 2024). "It would not be unexpected for patients with DOCK8 deficiency to have succumbed to severe infection or malignancy by his age." (PMID 41222818, 2025). "In summary, this report details a pediatric case of DOCK8 deficiency accompanied by severe, progressive herpetic infections non-responsive to standard antiviral and interferon therapies, yet responsive to siltuximab and glucocorticoid administration." (PMID 39044832, 2024). "Furthermore, genes involved in immunity and infection [e.g., chemokine ligand 19 (ccl19), dedicator of cytokinesis 8 (DOCK8), and intercellular adhesion molecule-1 (ICAM-1)] were also significantly dysregulated." (PMID 36984847, 2023). "Among the highly upregulated genes in both infection groups were ESPL1, DOCK8, ARID3A, PFKFB4, ANKZF1, BANP and GRB7, all of which exhibited a log2 fold change of ≥1.5." (PMID 37193047, 2022).
neurodevelopmental disorder (5 papers, 2017 to 2023). A behavioral and cognitive disorder with onset during the developmental period that involves impaired or aberrant development of intellectual, motor, or social functions. "A recent study sought to identify copy number variants across five neurodevelopmental disorders, and detected an enrichment for chromosome 9p24.3 duplication encompassing DOCK8 and KANK1 in affected individuals." (PMID 29241461, 2017).
genetic diseases (4 papers, 2022 to 2025). "Dedicator of cytokinesis 8 (DOCK8) deficiency is a genetic disorder affecting the migration of dendritic and specialized T cells in the skin, which can also lead to extensive lesions in MC." (PMID 41487758, 2025). "In the near future, we expect several genetic diseases such as DOCK8 deficiency, which lack efficient and safe treatment regimens, to be treatable with appropriate gene therapy strategies." (PMID 35373187, 2022). "Some of these such as the LRBA N815S, BLK R456C, and DOCK8 R1154C are only significant because of their observed occurrences in the context of other genetic diseases." (PMID 39415980, 2024).
bacterial infections (3 papers, 2014 to 2024). "Pathogenic bacterial infection results in CDC42-165aa overexpression encoded by circCDC42 in the lungs, which competitively binds with CDC42 to DOCK8, thereby inhibiting its activation of CDC42, ultimately aggravating Pyrin inflammasome activation and pyroptosis." (PMID 38977695, 2024).
infectious disease (2 papers, 2021 to 2023). A disorder directly resulting from the presence and activity of a microbial, viral, or parasitic agent in humans. "The comparison of significantly differentially regulated proteins between DOCK8 deficiency vs. AD identified a network pathway related to the developmental disorder, hereditary disorder, and infectious disease with the highest score (score 47)." (PMID 35386989, 2021).
adenocarcinoma (1 paper, 2016). A common cancer characterized by the presence of malignant glandular cells. "The upregulated expression of RSPO3, ADAMTS8 and DOCK8 was associated with the overall survival (all P < 0.05) and disease-free survival of adenocarcinoma patients (all P < 0.05), which indicated that RSPO3, ADAMTS8 and DOCK8 might influence the prognosis of adenocarcinoma." (PMID 27980454, 2016).
inflammation (1 paper, 2021). Aberrant reaction of the microcirculation characterized by movement of fluid and leukocytes from the blood into extravascular tissues. "At the same time, treatment with recombinant IL-21 provided Dock8 KO mice with marked protection from OVA-induced airway inflammation, accompanied by alleviation of inflammatory infiltration." (PMID 34867940, 2021).
metabolic disorders (1 paper, 2025). "These additional putative mono/oligogenic SLE genes are involved in type I IFN regulation (DDX58, NLRC4 and PACSIN1), disruption of B cell and T cell tolerance (DOCK8, FAS and LRBA) and metabolic disorders (CYBB, MAN2B1, SLC7A7)." (PMID 40386946, 2025).
neurodegenerative disease (1 paper, 2022). A disorder of the central nervous system characterized by gradual and progressive loss of neural tissue and neurologic function. "Importantly, DOCK8 deficiency reduced microglial phagocytosis and alleviated neuroinflammation in neurodegenerative disease models suggesting important roles of DOCK8 in microglia under pathological conditions." (PMID 35977943, 2022).
neurological disorders (1 paper, 2022). "Interestingly, DOCK8 mutations are associated with neurological disorders, such as CNS vasculitis, stroke and autism." (PMID 35977943, 2022). "DOCK8, a member of the DOCK family, functions as a guanine nucleotide exchange factor and plays key roles in immune regulation and neurological diseases." (PMID 35977943, 2022).
DOCK8 also shares sentences with these, for which no sentence is quoted: ataxia telangiectasia (5 papers); inflammatory bowel disease (4); epidermodysplasia verruciformis (3); Fanconi anemia (3); psychiatric disorder (3); sinusitis (3); WHIM syndrome (3); abscesses (2); common variable immunodeficiency (2); diabetes (2); dyskeratosis congenita (2); familial Mediterranean fever (2); nevus (2); X-linked agammaglobulinemia (2); acute myeloid leukemia (1); allergic asthma (1); Anxiety (1); arachnodactyly (1); attention deficit-hyperactivity disorder (1); autoimmune hepatitis (1); autoimmune lymphoproliferative syndrome (1); autoimmune polyendocrinopathy (1); autosomal dominant mental retardation (1); autosomal recessive disease (1); B-cell lymphocytic leukemia (1); bacterial pneumonia (1); bare lymphocyte syndrome (1); bipolar disorder (1); Blau syndrome (1); bleeding disorder (1).
A further 62 diseases each share a sentence with DOCK8 in 1 paper.